RESF1 (retroelement silencing factor 1)
Description:
Plays a role in the regulation of imprinted gene expression, regulates repressive epigenetic modifications associated with SETDB1. Required for the recruitment or accumulation of SETDB1 to the endogenous retroviruses (ERVs) and maintenance of repressive chromatin configuration, contributing to a subset of the SETDB1-dependent ERV silencing in embryonic stem cells.
Synonyms: C12orf35; KIAA1551; FLJ20696; FLJ10652; UTA2-1; GET
Tractability: PROTAC: UniProt records ubiquitination sites on it; ubiquitination databases record sites on it.
Gene: Protein-coding gene on chromosome 12 (31,959,370 to 31,993,114, forward strand). Ensembl gene ENSG00000174718.
Subcellular location: Nucleus
Subcellular location (Human Protein Atlas): Nucleoli; Nucleoli rim; Cytosol; Intermediate filaments
Gene Ontology:
Molecular function: protein binding; histone binding; histone methyltransferase binding
Biological process: transposable element silencing by heterochromatin formation
Cellular component: nucleolus; nucleus
Genetic constraint (gnomAD): Loss-of-function variants: 63 observed, 136.26 expected, observed/expected ratio (o/e) 0.46, 90% interval 0.38 to 0.57. The upper end of that interval is the gene's LOEUF score, 0.57, which puts it in group 2 of 6, group 1 being the genes least tolerant of losing a copy. Missense variants: 2,229 observed, 2,052.2 expected, observed/expected ratio (o/e) 1.09, 90% interval 1.05 to 1.12. Synonymous variants: 755 observed, 721.22 expected, observed/expected ratio (o/e) 1.05, 90% interval 0.99 to 1.11.
Homologues: Orthologues: chimpanzee RESF1 (98% identical), macaque RESF1 (93% identical), dog RESF1 (63% identical), pig RESF1 (60% identical), rabbit RESF1 (56% identical), mouse Resf1 (45% identical), rat Resf1 (42% identical).
Diseases named in the same sentence as RESF1 in open-access papers:
RESF1 is named in the same sentence as 17 diseases in open-access papers, as found by Europe PMC text mining. Sharing a sentence is not in itself a finding about the gene and the disease. The quoted sentences say what the papers report.
viral infection (2 papers, 2024 to 2025). "Several cancer-inducing factors stem from viral infections, while unavoidable complications during cancer treatment, such as tumor metastasis, organ compression, or chemotherapy, may lead to the overexpression of RESF1." (PMID 40608007, 2025).
autoimmune disease (1 paper, 2026). A disorder resulting from loss of function or tissue destruction of an organ or multiple organs, arising from humoral or cellular immune responses of the individual to their own tissue constituents. "This study identifies RESF1 as a novel gene associated with autoimmune disease in NSDTRs, ranging from isolated juvenile-onset AD to multi-organ autoimmune manifestations." (PMID 41813921, 2026). "The findings represent a rare example of monogenic autoimmune disease and establish RESF1 as a candidate gene for further investigation of immune tolerance mechanisms." (PMID 41813921, 2026).
breast carcinoma (1 paper, 2024). "In summary, here we present evidence that RESF1 is a chromatin-associated nucleoplasmic protein that functions as a tumor suppressor in ER- breast cancers." (PMID 38722825, 2024). "Reduction or loss of Resf1 may therefore be accelerating the terminal steps of breast cancer progression." (PMID 38722825, 2024). "Here, we have exploited the genomes of two different strains of mice that exhibit significantly different tumor phenotypes to identify and characterize RESF1 as a novel tumor suppressor for ER- breast cancer." (PMID 38722825, 2024). "Expression analysis in the human breast cancer METABRIC data set and in the autochthonous PyMT x MOLF/EiJ backcross tumor samples indicated that lower expression of Resf1 was associated with worse outcomes." (PMID 38722825, 2024). "Since transient transfections can nonspecifically target other compartments in the cell, attempts were made to stably transduce Resf1 constructs into six different mouse mammary tumor cell lines." (PMID 38722825, 2024). "The potential role of Resf1 in breast cancer metastasis is discussed here." (PMID 38722825, 2024). "However, the variable outcomes in sphere assays among mouse and human breast cancer cell lines suggest potential cell line-specific effects of RESF1 in stemness, challenging the notion that RESF1’s previously reported functions directly drive its metastatic phenotype." (PMID 38722825, 2024). "Furthermore, published DNase hypersensitivity (DHS) mapping data from the 3134 mouse mammary tumor cell line was mapped onto the Resf1 sequence and revealed two DHS sites, proximal to and overlapping the 5’ UTR, suggesting a potential promoter function in this region." (PMID 38722825, 2024). "The RNA expression data for human breast cancer available through the METABRIC consortium were consistent with this observation, as patients with ER- tumors and lower expression of RESF1 had worse outcomes than those with intermediate or high levels." (PMID 38722825, 2024). "qRT-PCR analysis of mammary tumor tissue from wildtype and gene trap x FVB/MMTV-PyMT littermates confirmed a reduction of Resf1 mRNA." (PMID 38722825, 2024).
coronary artery disease (1 paper, 2024). "RESF1 has been previously identified as a potential tumor suppressor and as a susceptibility locus for early-onset coronary artery disease in Japanese patients." (PMID 38722825, 2024).
graft versus host disease (1 paper, 2024). An immune system disorder that occurs after allogeneic hematopoietic stem cell transplant and is a reaction of donor immune cells against host tissues. "A previous study identified RESF1 as a minor histocompatibility antigen that could be exploited to prevent graft-versus-host disease." (PMID 38722825, 2024).
Hepatic steatosis (1 paper, 2022). Steatosis is a term used to denote lipid accumulation within hepatocytes. "Two genes were found highly significantly regulated: Lcn2, a potential biomarker for hepatic steatosis, damage, and inflammation, and Resf1, a factor regulator of epigenetics modification associated with SETDB1." (PMID 35327511, 2022).
infertile (1 paper, 2021). "NANOG is required to provide wild-type numbers of PGCs and is able to confer germline specification in the absence of instructive external signals, whereas Resf1 deletion causes infertility in both male and female mice." (PMID 34607919, 2021). "It will be interesting to investigate the contribution of RESF1 to germline development in vivo because Resf1-null mice are infertile." (PMID 34607919, 2021).
metastatic disease (1 paper, 2024). "The orthotopic allograft spontaneous metastasis assays in multiple cell lines from two different species, however, suggested that decreased Resf1 was associated with suppression of metastatic disease." (PMID 38722825, 2024). "In this study, Resf1 was selected for analysis because it was significantly associated with metastatic disease after quantitative trait locus analysis and is located near the maximum of the genetic susceptibility association peak." (PMID 38722825, 2024). "Reduction or loss of Resf1 accelerates tumor growth and increases the incidence and extent of metastatic tumors in the lung." (PMID 38722825, 2024). "ShRNA suppression of RESF1 in MDA-MB-231 cells implanted into nude mice significantly reduced metastatic disease." (PMID 38722825, 2024). "This interpretation was supported by the experimental cross between the Resf1 gene trap and the PyMT mouse, where animals with reduced Resf1 expression had higher incidence of metastatic disease and increased numbers of pulmonary metastases." (PMID 38722825, 2024). "The role of RESF1 in metastatic disease was further explored by using orthotopic transplants for spontaneous metastasis assays." (PMID 38722825, 2024). "The concordance of the results within the allograft or the GEMM autochthonous tumor samples and models suggests that Resf1 may have diametrically opposite effects on primary tumor growth and metastatic disease, as has been observed for TGFβ." (PMID 38722825, 2024).
tumor (6 papers, 2017 to 2025). "Consistent with the gene trap model, the reduction of Resf1 by CRISPR-mediated deletion was associated with increased tumor burden, more rapid tumor growth, and an increase in the number of pulmonary metastases." (PMID 38722825, 2024). "The association of Resf1 with these structures may be influencing the ability of tumor cells to undergo the epithelial-to-mesenchymal transition, which is thought to be critical for metastatic progression." (PMID 38722825, 2024). "Furthermore, an analysis of matched tail and primary tissues revealed loss of the wildtype copy in tumor tissue, consistent with Resf1 being a tumor suppressor." (PMID 38722825, 2024). "Moreover, genotyping analysis of matched tail and primary tumor samples from PyMT+/Resf1wt/wt and PyMT+/Resf1wt/KO F1 mice showed the loss of the wildtype allele in many of the animals, supporting the role of Resf1 as a tumor suppressor." (PMID 38722825, 2024). "Depletion of RESF1 results in increased tumor growth and metastasis, potentially through suppression of the EMT pathway." (PMID 38722825, 2024). "The Resf1 KO mouse was bred to the PyMT model to compare the tumor phenotypes of PyMT+/Resf1wt/wt and PyMT+/Resf1wt/KO compound heterozygous animals." (PMID 38722825, 2024). "Breeding this animal to the PyMT tumor model replicated the results from the gene trap experiment and the mouse and tumor Resf1 gene expression prognosis analysis." (PMID 38722825, 2024). "In this study, we expand upon these previous findings and provide evidence that an additional gene within this interval, Retroviral silencing factor 1 (Resf1), is a potential tumor suppressor and metastasis modifier in ER-negative breast cancer." (PMID 38722825, 2024). "Combined, these data suggest a complex dual role of Resf1 in tumor progression analogous to TGFβ, with functions as a tumor suppressor in the primary tumor but metastatic promoting abilities in the secondary site." (PMID 38722825, 2024). "The potential role of RESF1 as a tumor suppressor was identified by an analysis of homozygous deletions in 2218 primary tumors across 12 different human cancer types." (PMID 38722825, 2024). "Indeed, KM curves of mouse tumor expression data demonstrated that animals with lower Resf1 had worse survival." (PMID 38722825, 2024). "Thus, the in vivo suppression of the EMT transcriptional program in the Resf1 depleted autochthonous tumors is consistent with the increased tumor growth and decreased tumor latency." (PMID 38722825, 2024). "Alternatively, Resf1 may have opposing functions at the primary and secondary site, similar to Tgfβ which has previously been shown to have tumor suppressive functions at the primary site but pro-tumorigeneic effects for tumor invasion and metatasis." (PMID 38722825, 2024). "Alternatively, the decreased metastasis observed in the allograft models may result from an interaction of RESF1 depletion and a tissue culture-induced adaptation in the tumor cells." (PMID 38722825, 2024). "The gene expression-tumor phenotype correlation analysis indicated that variation in Resf1 expression might contribute to metastatic progression, consistent with the hypothesis that most inherited susceptibility is mediated by changes in gene expression rather than coding mutations." (PMID 38722825, 2024). "Together, these findings suggest that while RESF1 is significantly associated with the ribosomal biogenesis pathway, it may not play a major role in RESF1’s tumor suppressor functions." (PMID 38722825, 2024). "KD of RESF1 did not significantly alter primary tumor growth and significantly reduced lung metastasis, which is consistent with the findings from our 6DT1 and Mvt1 allografts." (PMID 38722825, 2024). "Therefore, while RESF1 may function as a minor histocompatibility antigen in tumor-graft rejection, it does not appear to play a significant role in metastatic progression, at least in the cell line-based orthotopic transplant spontaneous metastasis models." (PMID 38722825, 2024).
tumor (continued). "Because this gene-trap animal has not been extensively characterized and single-gene tumor expression studies can be confounded by amplifications or deletions that include additional genes that might influence the phenotype, we incorporated a second CRISPR-mediated Resf1 KO animal into the study." (PMID 38722825, 2024).
cancer (2 papers, 2024 to 2025). A tumor composed of atypical neoplastic, often pleomorphic cells that invade other tissues. "Fractionation of 4T1 and 6DT1 mouse cancer cells revealed that endogenous RESF1 was predominantly located in the nuclear fraction." (PMID 38722825, 2024). "Although utilizing RESF1 as a pivotal gene for cancer prediction could result in misunderstandings due to its ambiguous roles in various genetic processes, it is essential to further investigate its functions beyond cancer prediction, as this inquiry holds significant academic value." (PMID 40608007, 2025).
cardiovascular disease (1 paper, 2024). "The association of RESF1 with cardiovascular disease was identified in an exome-wide association study of 1,482 patients with cardiovascular disease and 5,774 healthy controls." (PMID 38722825, 2024).
RESF1 also shares sentences with these, for which no sentence is quoted: Addison's disease (1 paper); bladder cancer (1); bone metastasis (1); colitis (1); leprosy (1); triple-negative breast carcinoma (1).